IFIT3 (interferon induced protein with tetratricopeptide repeats 3)
Diseases named in the same sentence as IFIT3 in open-access papers (continued):
Sharing a sentence is not in itself a finding about the gene and the disease.
infection (continued). "Likewise, the 3’ UTRs of Ddx58, Ddx3x, Ddx21, Ifit2 and Ifit3, were significantly shorter in primary BMDMs from Cpsf6+/- mice, and such shortening was more pronounced upon VSV-eGFP infection." (PMID 38416782, 2024). "Finally, at 72 hours post-PIV3 infection, the transcriptional response remains interferon-centric, with continued expression of IFIT1, IFIT2, IFIT3, MX1, and OAS2." (PMID 39591472, 2024). "Finally, at 72 hours post-PIV3 infection, the transcriptional response remains robust and interferon-centric, with continued expression of IFIT1, IFIT2, IFIT3, MX1, and OAS2." (PMID 39591472, 2024). "In cluster 1, OAS2, IFIT3, IFI16, and DDX58 were higher in the rmIFNγR1-Ig treated animals at day 7, despite this cluster of genes being defined as genes that are highly induced at day 3 post-infection." (PMID 38950078, 2024). "Together, this demonstrated that the early secretion of mucosal IFN-α in non-immune horses promotes the upregulation of interferon-stimulated genes, including IFIT2 and IFIT3, while activation of this pathway seems unnecessary for EHV-1 immune horses to control and clear infection." (PMID 39162558, 2024). "Unlike IFIT1 and IFIT2, IFIT3 showed only a slight increase in citrullination during infection, which was not statistically significant (p = 0.06)." (PMID 38055760, 2023). "Notably, multiple antiviral proteins were also dramatically decreased in PAMs during the PRRSV-ADE infection, including ISG15, ISG20, IFIT1 (ISG56), IFIT2 (ISG54), IFIT3 (ISG60), IFIT5 (ISG58), OAS1, Mx1, RSAD2, TRIM22, TRIM25 and TRIM34, except for TRIM52." (PMID 36680075, 2022). "It would be interesting to determine if HAdV-C5 can establish a persistent infection in HDF cells utilizing IFNs in the absence of IFIT3." (PMID 34724821, 2021). "At the transcriptome level, the high expression levels of viral sensors MDA5 (IFIH1), R1G-1 (DDX58), and ISGS (ISG15, Mx1, Mx2, RSAD2, IFIT3, and IFIT5) and transcription factors like IRF-7 and STAT-1 that induce ISG expression were found in lymphocytes during virulent PPRV infection." (PMID 34631844, 2021). "Moreover, similar expression levels for several Interferon-stimulated genes (ISGs), namely Ifit1, Ifi44, Usp18, Ifit3 and Irf7, were observed in the livers of Ctrl and RKV-supplemented mice at various time points after infection." (PMID 33294789, 2020). "As compared with polyI:C, AiV induced a lower level of antiviral gene expression, with huge differences in the level of IFNβ, Viperin, RIG-I, MDA5, IFN induced protein with tetratricopeptide repeats 3 (IFIT3) and CXCL10 between AiV infection and polyI:C stimulation." (PMID 32802187, 2020). "Our main findings were: 1) the host immune response was initiated only in fetuses with detectable levels of PRRSV; 2) upon infection of fetal thymus, a set of core responsive IFN-inducible genes (CXCL10, IFIH1, IFIT1, IFIT3, ISG15, and MX1) were strongly upregulated in both tissues." (PMID 33148169, 2020). "Treatment of PBMCs with MA (in the absence of infection) led to the induction of IFIT2, IFIT3, and OAS genes; they are associated with categories Interferon alpha/beta Signaling (p-value = 7.25E-4) and Interferon Signaling (p-value = 7.76E-3)." (PMID 31796757, 2019). "One potential hypothesis is that dysregulation of ISG induction, perhaps due to infection, could perturb the balance of IFIT2 and IFIT3, promoting cell death to restrict pathogen spread." (PMID 29554348, 2018). "As reflected by differences in respective protein levels, numerous members of this pathway were up-regulated by T3D infection but not by T1L infection, and Mx1 and IFIT3 were down-regulated by UV-T3D treatment." (PMID 25905045, 2015). "Unlike other ISGs, IFIT3 was not expressed in TKO macrophages even at 48 hours after infection, despite being induced in DKO macrophages." (PMID 23300459, 2013).
infection (continued). "Also, it was important to discuss thatthough our study identified a total of 9 genes that were common among three stages, but only 6 of them (OASL, IFI27, IFIT1, IFIT3, RSAD2and IFI44L) made into the PPI network whose expression level increases with the increase in the level of infection." (PMID 40255307, 2025). "The infection with viral strains that were only defective in the expression of MHC immune evasion genes US2, US3, US6, and US11 still showed some reduction in the steady-state levels of ISGs Mx1 and ISG15, but also showed slightly elevated levels of IFIT3, compared to the wt-control virus." (PMID 40143353, 2025). "Additionally, the T677A virus induced higher expression of interferon stimulated genes (ISG) (RIG-I and IFIT3) at 48 hours post-infection in wild-type HEK293-luc cells, but not in RIG-I −/− or MAVS −/− cells." (PMID 39605425, 2024). "We show that the expression of the interferon-stimulated proteins MX1, IFIT1, IFIT3 and ISG15, as well as expression of defense response proteins DDX58, STAT1, OAS3, EIF2AK2 and SAMHD1 was significantly up-regulated in these cells upon infection with either virus." (PMID 30959732, 2019). "Analysis of average infection-induced changes to total proteome abundance revealed that, in contrast to IAV, both IBV and IAVΔNS1 infections triggered a classical host IFN response consisting of several ISG products, including ISG15, ISG20, MDA5, MxA, IFIT1, and IFIT3." (PMID 31391303, 2019). "Similarly, TFIIB depletion after infection with rTHOV-ΔML (mixed stimulus) led to a decreased IFIT3 expression, but not STAT1, p65 or p38." (PMID 29709033, 2018). "Notably, the initial temporary upregulation of IFN-α, IFIT3, and IFIT5 in MVECs was observed, which may be attributed to the stress reaction of the innate immune response in MVECs to HP-PRRSV at the early stage of infection." (PMID 36146725, 2022). "As with VSV, neither IFIT2 nor IFIT3 alone exerted an antiviral effect on PIV3, but their co-expression significantly inhibited infection." (PMID 41093992, 2025). "Similar to the lab-adapted strains, we observed six ISG-related DAPs (IFIT1, IFIT2, IFIT3, OAS3, ISG15, and MX1) significantly upregulated compared to MOCK infected UNOs, upon infection with clinical isolates of PeV-A3, but not PeV-A1." (PMID 38514653, 2024). "The A549 cells lacking the XRN1 protein showed increased IFN-β, IFIT1, IFIT3, and ISG15 expression compared with the A549 control cells at 4 to 8 h after WSN infection." (PMID 34311580, 2021). "Expression of eight of these genes (IFIH1, OAS2, IFIT1, IFIT2, IFIT3, IFIT5, USP18 and DDX58F) was significantly elevated in response to VSV-ΔM51 infection in permissive cells, but not in resistant PDACs." (PMID 27533247, 2016). "Within 6 h of infection, DV already gained capacity to downregulate although non-significantly IFN-α-induced IFIT3 expression." (PMID 24223959, 2013). "In the present study, we observed that several ISGs with known or proposed anti-CCHFV activity, i.e., Mx1, ISG15 and ISG20 or not defined for CCHFV like IFIT1, IFIT3, IFITM3, IFI16, and OAS3 were upregulated in the acute phase CCHFV patient samples as well as in the cell-infection model." (PMID 35437144, 2022). "Results showing that IFIT1, IFIT2, and IFIT3, but not IFIT5, were induced with similar kinetics by DV infection suggest the possibility of co-regulation, and also the coordination and non-redundant functioning of these molecules in IFN-mediated signaling events, as observed in neurons." (PMID 24223959, 2013). "However, IFIT2, IFIT3, and IFN-α were not increased in immune horses at any time after infection." (PMID 39162558, 2024).
tumor (58 papers, 2014 to 2026). "These analytical results strengthen the association between the downregulation of IFIT3 expression and tumor progression in LUAD, providing important clues for further research into the function and potential role of IFIT3." (PMID 39139574, 2024). "The ISGs, IFIT1 and IFIT3, are implicated in important functions in tumor development, and serve as biomarkers for various cancers." (PMID 35280763, 2022). "H&E staining of tumor sections revealed a more profound desmoplastic reaction with larger areas of connective tissue in tumors from mice that received the IFIT3 overexpressing variant of COLO357FG cells as compared to the empty vector controls." (PMID 25650658, 2015). "However, other studies suggest that IFIT3 can act as a tumor suppressor in hematological malignancies and is associated with favorable clinical outcomes." (PMID 40564154, 2025). "Notably, IFN T cells exist in the NPC_PT and NPC_LNM samples, where their highly expressed IFIT1 and IFIT3 genes have been proven to be associated with tumour growth and metastases." (PMID 39392128, 2024). "Beyond its crucial role in cancer progression, IFIT3 is intricately involved in key immune pathways, making it a critical player in both antiviral defense and tumor-immune dynamics." (PMID 40061935, 2025). "Potential tumor suppressive properties of IFIT3 in hematological malignancies are also highlighted by other studies." (PMID 40564154, 2025). "In this cancer type, increased IFIT3 expression promoted tumor growth, invasion, metastasis, EMT and a pro-inflammatory tumor microenvironment, as well as resistance to chemotherapy and targeted therapy." (PMID 40564154, 2025). "This dual regulatory role of IFIT3 in both inflammation and tumor progression underscores its complex functions in tumor immunomodulation." (PMID 40061935, 2025). "As a key immunoregulatory molecule, IFIT3 has demonstrated its important role in tumorigenesis, development, and immune escape, and has become a hotspot of tumor immunity research in recent years." (PMID 40061935, 2025). "IFIT3 showed a strong correlation with neutrophil and dendritic cell infiltration levels in the tumor microenvironment." (PMID 40061935, 2025). "Recent studies have demonstrated that IFIT3 plays a crucial role in antiviral immunity, tumor microenvironment regulation, immune evasion, and inflammatory responses." (PMID 40061935, 2025). "Given IFIT3’s central role in both immune evasion and inflammation-mediated tumor progression, it emerges as an attractive candidate for targeted cancer immunotherapy approaches." (PMID 40061935, 2025). "This figure illustrates how IFIT3 influences tumor progression through NF-κB activation, PD-L1 regulation, inflammatory cytokine secretion, and immune cell modulation, ultimately shaping an immunosuppressive microenvironment." (PMID 40061935, 2025). "We observed significant upregulation of the transcriptional levels of Ifnb1, Ifit1, Ifit2, Ifit3, Irf7, and Mx1 in irradiated 4T1 tumor tissues and irradiated CT26, H22, and GL261 carcinoma cells." (PMID 40470716, 2025). "IFIT3 facilitates immune evasion and promotes inflammation-mediated tumor growth by regulating immune checkpoints and the tumor microenvironment, its emerging role as a target for cancer immunotherapy opens new avenues for therapeutic strategies." (PMID 40061935, 2025). "By upregulating PD-L1, IFIT3 facilitates tumor immune evasion by suppressing cytotoxic T-cell function, thereby impairing anti-tumor immune responses." (PMID 40061935, 2025). "By regulating key processes such as cell proliferation, invasion, immune checkpoint modulation, and inflammation, IFIT3 has emerged as a critical player in tumor immunity." (PMID 40061935, 2025).
tumor (continued). "A key mechanism by which IFIT3 modulates tumor immunity is through its interaction with immune checkpoint molecules, particularly programmed death ligand 1 (PD-L1)." (PMID 40061935, 2025). "A summary of the tumor-specific mechanisms involving IFIT3 is provided in, highlighting its role in different cancer types." (PMID 40061935, 2025). "These molecular cascade reactions represent a key mechanism through which IFIT3 drives tumor progression and metastasis in HNSCC." (PMID 40061935, 2025). "Among interferon-inducible proteins, IFIT3 has garnered significant attention in recent years due to its dual role in innate immunity and tumor regulation." (PMID 40061935, 2025). "Studies on the involvement of IFIT3 in immune escape, tumor microenvironment regulation, and inflammation are gradually revealing its potential as a target for cancer immunotherapy." (PMID 40061935, 2025). "Interferon-Induced Protein with Tetratricopeptide Repeats 3 (IFIT3) plays a dual role in innate immunity and tumor immunity, functioning as both a viral defense molecule and a regulator of tumor progression." (PMID 40061935, 2025). "The literature has reported the involvement of IFIT3 in various pathological processes, including certain inflammatory responses and tumour development." (PMID 39305055, 2024). "Animal studies were performed to analyze the effect of IFIT3 on tumor growth and metastasis of HNSC in vivo." (PMID 38273364, 2024). "IFIT3 knockdown markedly inhibited the growth of tumor volume and decreased tumor weigh in xenograft nude mice model compared to the control, and the growth of xenograft tumors was significantly promoted by IFIT3 upregulation." (PMID 38273364, 2024). "Meanwhile, immune-activated cells and markers, such as anti-tumor T cells, neutrophils, and Th1 cells, also exhibit a positive correlation with IFIT3 expression." (PMID 39139574, 2024). "We analyzed data from the TCGA database and the GSE116959 GEO database, assessing the mRNA expression levels of IFIT3 in LUAD tissue and non-tumor tissue, and validated the protein-level expression of IFIT3 in LUAD using the Human Protein Atlas (HPA) database." (PMID 39139574, 2024). "Function assay indicated that IFIT3 promoted malignant behaviors in vitro, as well as tumor growth and lung metastasis in vivo." (PMID 38273364, 2024). "Human neutrophil cluster 6 highly expressed the all signatures of mouse Ifit3+ neutrophils and specially appeared in the tumor group." (PMID 37483625, 2023). "Intriguingly, IFIT3 characterized the molecular dynamics of tumor progression and predicted shortened OS of patients in our study, suggesting IFIT3 itself as a potential candidate biomarker and progression landmark for EOC." (PMID 38016970, 2023). "On the contrary, the high expression of IFIT1 and IFIT3 in OSCC contributes to gefitinib's anti-tumor effect by enhancing p-EGFR recycling." (PMID 37980495, 2023). "Ectopic expression of IFIT1 or IFIT3 in OSCC cells promoted tumor growth and metastasis by activating EGFR signaling." (PMID 31921891, 2019). "Biomarker expression of CXCR4, SMAD4, SOX9 and IFIT3 will be prospectively assessed by immunohistochemistry and verified by rt.-PCR from tumor and adjacent healthy pancreatic tissue of surgical specimen." (PMID 28356064, 2017). "These samples are used to confirm immunohistochemistry analysis using reverse transcription quantitative polymerase chain reaction (RT-qPCR) as a second method to analyze CXCR4, SMAD4, SOX9 and IFIT3 mRNA expression of the tumor." (PMID 28356064, 2017). "We have found that overexpression of IFIT3 enhances tumor growth, angiogenesis, metastasis and chemoresistance in vitro and therefore IFIT3 seems to be a tumor promoting protein." (PMID 28356064, 2017).
tumor (continued). "We now show that IFIT2 and other family members IFIT1 and IFIT3, when overexpressed in tumor cells, enhance T-cell killing of tumor cells." (PMID 28878208, 2017). "The role of IFIT3 in hematologic malignancies appears to be complex, where it might act as a pro-oncogene or tumor suppressor depending on the type of disease." (PMID 40564154, 2025). "Strategies aimed at inhibiting IFIT3 function or blocking its interaction with key immunoregulatory pathways, such as NF-κB and PD-L1, may enhance anti-tumor immune responses." (PMID 40061935, 2025). "This suggests that LOXL2 may regulate the expression of IFIT3, which has important implications for tumor progression." (PMID 40061935, 2025). "Role of IFIT3 in cancer progression: tumor-specific mechanisms." (PMID 40061935, 2025). "Of interest is the unique role of IFIT3 in the remodeling of the tumor microenvironment, the regulation of inflammatory response, and the modulation of immune checkpoint molecules, suggesting that it has an important potential for clinical application in tumor immunotherapy." (PMID 40061935, 2025). "Additionally, studies showed that N-myc and STAT interactor (NMI) promoted IFIT3 expression and accelerated tumor growth and migration by activating the STAT3-IFIT3 signaling pathway." (PMID 40061935, 2025). "Finally, this paper underscores IFIT3’s potential clinical applications in the modulation of tumor immunity, highlighting the need for further research on IFIT3-targeted therapies." (PMID 40061935, 2025). "Meanwhile, IFIT3 over-expression promoted tumor growth and metastasis of HNSC in vivo." (PMID 38273364, 2024). "The results showed differential expression of IFIT3 in various tumor tissues." (PMID 39139574, 2024). "Furthermore, we found that the expression levels of IFIT3 increased with higher tumor grades, suggesting a correlation between IFIT3 and tumor grade, indicating its potential role in the development of LUAD." (PMID 39139574, 2024). "To delve deeper into the regulatory mechanisms of IFIT3 in malignant tumor progression and immune infiltration, we combined the KEGG results and identified a potential pathway: the JAK3-STAT pathway, which may be associated with IFIT3." (PMID 39139574, 2024). "Additionally, IFIT3 promoted the formation of tumor spheroids and enhanced HNSC cells’ capacity to start tumors." (PMID 38273364, 2024). "Finally, Cluster 8 was equally conserved across healthy and tumor-associated neutrophils and was enriched for IFN markers: Isg15, Rsad2, Ifit3, Ifit1, and Slfn4, a phenomenon previously reported in several scRNA-seq studies of neutrophils." (PMID 38358352, 2024). "Our research suggests that IFIT3 has tumor-suppressive effects, while UBE2O acts as an oncogene." (PMID 38129382, 2023). "In present study, we performed multiplexed IF staining experiment to preliminary explore whether IFIT1/IFIT3+ T cells play tumor‐promoting or cytotoxic roles in lymph node metastasis." (PMID 36709495, 2023). "Moreover, STAT1 is known to have a tumor suppressor role whereas IFIT3 has been shown to play a dual role in cancer." (PMID 34622927, 2021). "Therefore, it is conceivable that the αvβ6 integrin down-regulates IFIT3 as a mechanism to promote tumor growth." (PMID 34622927, 2021). "As multiple studies have demonstrated that tumor infiltrating neutrophils are related to cytotoxic T cells in various ways, we confirmed that our identified IFIT3+N5, a subtype of neutrophil, was enriched in ICB responders and showed positive correlation with CTL." (PMID 34659209, 2021). "We found that this way of assessment of IFN response is more sensitive, since in some tumor cells (e.g. HCT116) even treatment with IFN alpha did not cause induction of IFIT3, while ISRE reporter activity was easily detected." (PMID 29400649, 2018). "Here we provide data that IFIT3 also represents a candidate tumor promoting gene." (PMID 25650658, 2015).